IL6 (interleukin 6)
Diseases named in the same sentence as IL6 in open-access papers (continued):
Sharing a sentence is not in itself a finding about the gene and the disease.
schizophrenia (continued). "Interestingly, our results indicated that IL-6 and IL-10 levels were both correlated with BMI in schizophrenia patients (r = 0.233, P = 0.010; r = 0.204, P = 0.025, respectively)." (PMID 33324265, 2020). "Elevated IL-6 levels in childhood might lead to the development of schizophrenia in young adulthood 30, and significant correlations have been found between anti-inflammatory IL-4 and IL-10 with negative symptoms in EOS patients." (PMID 32038109, 2020). "In addition, after 6 weeks of treatment with four different atypical antipsychotics (risperidone, amisulpride, olanzapine, and aripiprazole), patients with schizophrenia exhibited a significant reduction of plasma IL-6 and TNF- α." (PMID 32061259, 2020). "Although this may initially be counterproductive in people with schizophrenia (who usually have high IL-6 and inflammation levels), with regular exercise (and the resulting increased adaptative fitness) a chronic response could be achieved." (PMID 30678202, 2019). "Patients with first episode of schizophrenia as well as its relapse were reported to have increased serum level of IL-6, tumor necrosis factor α, IL-1β, and interferon-γ and decreased serum concentration of anti-inflammatory interleukin-10 (IL-10) (Müller 2018)." (PMID 30178287, 2019). "Similar results have been reported previously in a sub-sample of the present study, which found associations between sTNF-R1, IL-1Ra, OPG, IL-6 and severity of mood symptoms only in patients with bipolar disorders, but not in schizophrenia." (PMID 29721726, 2019). "Although there is evidence for the positive effects of physical exercise on schizophrenia, more studies will be required to better understand how variation in different exercise parameters affects both the acute and chronic plasma levels of IL-6." (PMID 30678202, 2019). "Long-term treatment of olanzapine caused metabolic symptoms, including IR, by markedly elevating the plasma levels of pro-inflammatory cytokines, including IL-1ß, IL-6, IL-8 and TNFα; these findings are consistent with observations from schizophrenia patients chronically treated with olanzapine." (PMID 30733507, 2019). "However, the interaction of multiple factors in the immune system mean that doubts remain about the exact mechanisms which interrelate it with schizophrenia and exercise, although recent work has emerged highlighting an important role for IL-6 in this context." (PMID 30678202, 2019). "Considering that IL-6 plays a major role in the development and advancement of schizophrenia, it is possible that the behavior of IL-6 levels in response to exercise may explain its beneficial effects on this disease which are evident in many studies." (PMID 30678202, 2019). "Population-based longitudinal studies have reported associations of elevated concentrations of CRP, IL-6 and erythrocyte sedimentation rate (ESR) in childhood, adolescence or young adulthood with risk of psychotic symptoms or diagnosis of schizophrenia subsequently in adulthood." (PMID 31563954, 2019). "Moreover, studies of cerebrospinal fluid (CSF) have shown increased levels of pro-inflammatory markers in schizophrenia patients when compared with healthy controls, including IL-1β, IL-6 and S100B." (PMID 30355368, 2019). "Many other interesting substances, such as anti-cytokines, anti-Il-6 complex substances, minocycline, and statins, that target various components of the immune system may be beneficial in MD or schizophrenia or both." (PMID 31214060, 2019). "Looking more specifically at the different symptoms of schizophrenia, it appears that high levels of inflammation and IL-6 are associated with the disease’s negative symptoms." (PMID 30678202, 2019). "Furthermore, in chronic patients, IL-6, soluble IL-2 receptor, and IL-1β were similarly elevated in schizophrenia and bipolar groups compared to controls." (PMID 29803226, 2018).
schizophrenia (continued). "One study conducted by the group of Brian Miller at Augusta University in Georgia, plans to randomize 30 stable outpatients with schizophrenia or schizoaffective disorder with CRP >5 mg/L to adjunct treatment with siltuximab which is a recombinant IL-6 monoclonal antibody, or placebo." (PMID 30766494, 2018). "Additionally, cumulative exposure to antipsychotic medication over the lifespan (dose times duration) was significantly related to IL-6 (rs = .271, p = 0.041) and IL-12 (rs = .274, p = 0.036) in patients with schizophrenia." (PMID 29803226, 2018). "However, as IL-6 seems to be both pro- and anti-inflammatory, more research is needed to establish the usefulness of IL-6 as a biomarker in schizophrenia." (PMID 30766494, 2018). "Elevated IL-6 levels have also been linked to schizophrenia and were especially related to negative symptoms." (PMID 29434554, 2018). "One of the possibilities in drug development for the treatment of schizophrenia might be the tissue-specific IL-6 blockade, thus avoiding systemic side effects of this kind of treatment." (PMID 29163240, 2017). "While the underlying cause of the cytokine dysregulation we have found here is not known, decreased IL-2, increased IL-6, IL-8 and TNFα have all been associated with Toxoplasma gondii infections, of which the seroprevelance is increased in schizophrenia." (PMID 28923068, 2017). "Also, increased levels of IL-6 were found only in those patients with schizophrenia that had a positive childhood trauma history." (PMID 29163240, 2017). "Higher IL-6 levels showed to be related with cognitive decline in schizophrenia." (PMID 29163240, 2017). "The magnitude of increase in IL-1β, IL-6, IL-8 and IL-10 mRNAs in people in the elevated inflammation biotype ranged from 100 to 220% of those in the non-elevated inflammatory biotype and was comparable between control and schizophrenia groups." (PMID 28923068, 2017). "The first meta-analysis of cytokine levels in schizophrenia patients has concluded that IL-6 levels are increased, but recent meta-analysis has pointed out that IL-6 is increased in first-episode psychosis and acute relapse, and can be used as a state marker of schizophrenia." (PMID 29163240, 2017). "Beneficial effects of immunomodulatory therapy in schizophrenia have been already shown and the use of tissue-specific inhibitors of IL-6 or other IL-6-targeted therapy could possibly be useful in the treatment of schizophrenia and comorbid somatic states." (PMID 29163240, 2017). "However, it is possible that only exposure to IL-6 and CRP in a specific window of time (eg, early life) affects schizophrenia risk." (PMID 29094161, 2017). "Mechanisms underlying the association of blockade of IL-6 classic signaling and lower CRP levels with increased risk of schizophrenia are unknown." (PMID 29094161, 2017). "Single nucleotide polymorphisms have been analysed in many cytokines, in particular, those that are associated with altered levels in schizophrenia such as TNF-α, IL1-β, IL-6, IL-10, INF-γ, and in the genes encoding the immune system regulatory proteins CTLA-4 and CD28." (PMID 29317797, 2017). "However, we observed that serum level of IL-6 had significantly decreased after antipsychotic treatment in patients with first-episode psychosis and schizophrenia in relapse." (PMID 29163240, 2017). "Likewise, direct IL-6 inoculation into pregnant rodents also induces schizophrenia-like abnormalities in the offspring." (PMID 28620379, 2017). "As such, interleukin 6 (IL-6), which can function as both a pro- and anti-inflammatory cytokine- has been examined for its role in the development, course, symptomology, and applicability as a biomarker of schizophrenia." (PMID 27206977, 2016). "The mean value for PBMC IL-6 mRNA levels in participants with schizophrenia is 5.64 ± 3.0." (PMID 27206977, 2016).
schizophrenia (continued). "Our results demonstrate that IL-6 mRNA levels from freshly extracted PBMC are significantly upregulated in participants with schizophrenia when compared to healthy controls, thereby confirming our hypothesis." (PMID 27206977, 2016). "Additionally, we attempted to elucidate the role of IL-6 in disease onset and symptom presentation in schizophrenia." (PMID 27206977, 2016). "Future utilization of peripheral IL-6 mRNA levels could be clinically useful during an initial diagnosis and help tailor individualized treatment plans for patients with schizophrenia." (PMID 27206977, 2016). "They established that pro-inflammatory cytokine levels are constantly augmented in patients with schizophrenia and stated that pro-inflammatory cytokines like IL-6, IL-12, TNF-α, IL-1β, and IFN-γ are elevated in the blood and CSF in initial-onset and acute-relapse patients with schizophrenia." (PMID 27047333, 2016). "For this analysis, the area under the ROC curve (AUC) represents the predictive value of using only PBMC IL-6 mRNA levels to accurately differentiate between participants with schizophrenia and healthy controls across all of IL-6 mRNA levels found in our sample." (PMID 27206977, 2016). "Furthermore, in participants with schizophrenia, we also found elevated levels of IL-6 mRNA with earlier ages of illness onset and worse positive symptom presentation, as measured by the Positive and Negative Syndrome Scale." (PMID 27206977, 2016). "The expression levels of IL6 were unchanged between control and schizophrenia samples (P=0.25)." (PMID 27801899, 2016). "IL-6 levels measured in the serum, as in the Frydecka paper, can originate from multiple tissues, including adipose, muscle and liver, with particularly confounding effects given the well known metabolic disturbances in the schizophrenia population." (PMID 27206977, 2016). "There is scarcity of studies looking into clinical correlates of IL-6 alterations in schizophrenia." (PMID 25214388, 2015). "An injection of IL-6 in pregnant mice also results in the development of impairments in PPI and latent inhibition in the adult offspring, both of which are linked to schizophrenia and ASD." (PMID 26633355, 2015). "In particular, increased GFAP in schizophrenia/psychotic symptoms could be closely related to increased neuroinflammatory markers, as well as to increased IL-1beta and IL-6 serum levels." (PMID 25889039, 2015). "The influence of the immune system deregulation on the risk of schizophrenia has been reported for years now; however, the association between CRP and IL-6 with schizophrenia course and symptomatology, as well as with cognitive functioning has not been shown so far." (PMID 25214388, 2015). "Interestingly, the regulation of IL-6 production by this polymorphism is more pronounced in neonates than in adults, indicating that rs1800795 might play a prominent role in determining the inflammatory response during the phases of early environmental adversities in pathogenesis of schizophrenia." (PMID 24787542, 2014). "There is a substantial lack of knowledge on how genetic predisposition to elevated IL-6 expression effects hippocampal structure in schizophrenia patients." (PMID 24787542, 2014). "Thus, several lines of evidence as reviewed above implicate a compelling role for elevated IL-6 in the pathogenesis of schizophrenia possibly through disruption of prenatal hippocampal development." (PMID 24787542, 2014). "Notably, we were unable to find a significant association between the remaining polymorphisms (IL2 −330T>G, IL6 −174G>C, IFNG +874T>A, TGFB1 +913G>C) and schizophrenia in our study." (PMID 24065520, 2013). "Increased levels of interleukin-6 (IL-6) and the activation of the IL-6 system in schizophrenia might be the result of the activation of monocytes/macrophages, too." (PMID 23724961, 2013).
schizophrenia (continued). "In addition, overproduction of IL-6 has been found to correlate with clinical indices of schizophrenia and antipsychotic treatment decreases the plasma level of IL-6." (PMID 24065520, 2013). "In addition, Interleukin (IL)-6 serum levels were significantly increased in patients with schizophrenia as compared with controls, whereas IL-10 concentration was increased in both patients with schizophrenia and BPD." (PMID 22505994, 2012). "Moreover, elevated serum levels of IL-6 have been detected in individuals with schizophrenia and schizoaffective disorder, together with their first-degree family members with mood disorders, suggesting an activated inflammatory response possibly driven by viral agents." (PMID 40806558, 2025). "However, when tested separately, higher levels of plasma IL-6 were significantly related only to more severe depressive symptoms in those with early schizophrenia (B = 0.89; 95% CI, 0.25 to 1.52; p = .006), but not in established schizophrenia (B = 0.49; 95% CI, −0.22 to 1.20; p = .178)." (PMID 39911538, 2025). "In this study, we examined whether elevated levels of plasma IL-6, an inflammatory protein, are associated with more severe depressive and negative symptoms in schizophrenia." (PMID 39911538, 2025). "Our results indicate that higher plasma IL-6 levels may be differently associated with the severity of depressive and negative symptoms in schizophrenia depending on the illness stage." (PMID 39911538, 2025). "The GLM analyses demonstrated significant associations between higher plasma IL-6 levels (natural log and z-scored) and more severe depressive symptoms in early schizophrenia and negative symptoms in established schizophrenia (the latter in the absence of a significant moderation effect)." (PMID 39911538, 2025). "Finally, our findings are not directly comparable to studies that have investigated cerebrospinal fluid IL-6 levels in schizophrenia, which have not addressed an association with negative and depressive symptoms." (PMID 39911538, 2025). "However, the association between higher IL-6 levels and the severity of negative symptoms in established schizophrenia was observed in the absence of a moderation effect; therefore, the findings should be interpreted carefully." (PMID 39911538, 2025). "Furthermore, in the same experimental conditions, we measured the expression levels of the main pro−inflammatory cytokines regulated by NF−kB (i.e., IL6, TNFα, and IL1β), given their proven role in the etiopathogenesis of several psychiatric diseases, including schizophrenia." (PMID 37240042, 2023). "In addition, IL-6 levels of peripheral blood were higher in schizophrenia patients (all P < 0.05)." (PMID 38066312, 2023). "Minocycline adjunctive therapy may be beneficial in schizophrenia, with documented improvement in cognitive, positive, and negative symptoms and reduction of inflammatory cytokines IL-1β and IL-6." (PMID 38259293, 2023). "Moreover, we found that IL-6, glucose metabolism, and B cell infiltration may be common pathways between schizophrenia and IS." (PMID 37305753, 2023). "Hence, we speculated that sex hormones and IL-6 might play different roles in the pathophysiological processes of schizophrenia in males and females." (PMID 37370004, 2023). "However, our previous study used some of the same groups of patients and controls; it found that, in multiple binary logistic regression, taking into account age, BMI and IL-6, participants with higher IL-6 had greater odds of having schizophrenia (all else being equal;)." (PMID 36362580, 2022). "Signs of a peripheral inflammatory response in schizophrenia are indicated by elevated serum/plasma levels of certain pro-inflammatory factors, including prostaglandin E2 and C-reactive protein, as well as some pro-inflammatory cytokines, such as IL-1β, IL-6, IL-8, and tumor necrosis factor-α." (PMID 35722585, 2022).
schizophrenia (continued). "Furthermore, circulating levels of IL-6 have also been shown to decrease after antipsychotic treatment, hypothesizing their use as possible biomarkers of response to treatment in schizophrenia." (PMID 35963926, 2022). "Additionally, evidence suggests a significantly reduced variability in its levels compared to HC, which may indicate that elevated levels of IL-6 is a key element of the schizophrenia immunophenotype." (PMID 34501305, 2021). "The polymorphism of the IL6 (-174G/C) gene does not elevate the level of IL-6 in the serum, but it has been shown to be associated with the occurrence and severity of positive symptoms in the course of schizophrenia." (PMID 34501305, 2021). "Mendelian randomisation (MR) studies have reported associations of genetic variants regulating inflammatory biomarkers such as interleukin-6 (IL-6) with schizophrenia, suggesting that inflammation may be associated with schizophrenia beyond any effects of confounding." (PMID 32828613, 2020). "Intraperitoneal administration of interleukin (IL)-1β, IL-6, and IL-2 in mice was shown to stimulate dopamine (DA) utilization in prefrontal cortex, leading to DA deficiency, which is connected with negative symptoms in schizophrenia." (PMID 30178287, 2019). "As for older paternal age, it has been suggested that the observed increased incidence of ASC, schizophrenia and bipolar disorder could be the result of immune dysregulation with increases in pro-inflammatory cytokines IL-1β and IL-6 observed in all three disorders." (PMID 31719968, 2019). "In this article we examine the relationships between schizophrenia, exercise, and the immune system, and specifically look at the current evidence regarding IL-6 as one of the potential mechanisms through which exercise could produce improvements in the symptoms of schizophrenia." (PMID 30678202, 2019). "Furthermore, IL-6 was shown to be increased prior to the onset of schizophrenia." (PMID 29434554, 2018). "Moreover, IL-6 is able to activate the kynurenine pathway leading to an increase of the kynurenic acid production, a compound that has been consistently reported at elevated levels in the CSF or in the post-mortem brain of patients with schizophrenia." (PMID 29228979, 2017). "Finally, IL-6 levels may be a useful biomarker for a diagnosis of schizophrenia due to the predictive capabilities we demonstrate here." (PMID 27206977, 2016). "Thus, overexpression of pro-inflammatory cytokine IL-6 may be a factor for schizophrenia development in our population." (PMID 27177030, 2016). "Therefore, we cannot determine as to whether obtained correlations between IL-6 level and cognitive performance are specific for schizophrenia patients." (PMID 25214388, 2015). "Together with the fact that we have found the relationship between higher IL-6 levels and cognitive decline in schizophrenia, it could be inferred that IL-6 may serve as a potential inflammatory biomarker accompanying neurodegenerative processes leading to cognitive deterioration in schizophrenia." (PMID 25214388, 2015). "Interestingly, emerging evidence indicates that IL-6 level is increased already in subjects with at-risk mental state (ARMS) and might be a marker of transition from ARMS to schizophrenia." (PMID 25214388, 2015). "Interestingly, some cytokines [IL-12, IFN-γ, TNF-α, soluble IL-2 receptor (sIL-2R)] may be trait markers for schizophrenia, while others are raised during phases of intensified symptoms (IL-1β, IL-6, and TGF-β)." (PMID 24550848, 2014). "Pro-inflammatory changes include elevated serum measures of pro-inflammatory cytokines [interleukin (IL)-1β, IL-6, IL-8, TNF-α] and other pro-inflammatory factors [prostaglandin E2 (PGE2), CRP] and elevated monocyte counts and activated immune cells have been associated with schizophrenia." (PMID 24550848, 2014).